EZH1 (enhancer of zeste 1 polycomb repressive complex 2 subunit)
Description:
Polycomb group (PcG) protein. Catalytic subunit of the PRC2/EED-EZH1 complex, which methylates 'Lys-27' of histone H3, leading to transcriptional repression of the affected target gene. Able to mono-, di- and trimethylate 'Lys-27' of histone H3 to form H3K27me1, H3K27me2 and H3K27me3, respectively. Required for embryonic stem cell derivation and self-renewal, suggesting that it is involved in safeguarding embryonic stem cell identity. Compared to EZH2-containing complexes, it is less abundant in embryonic stem cells, has weak methyltransferase activity and plays a less critical role in forming H3K27me3, which is required for embryonic stem cell identity and proper differentiation.
Synonyms: KIAA0388; KMT6B
Tractability: Small molecule: a high-quality ligand is known. PROTAC: UniProt records ubiquitination sites on it; ubiquitination databases record sites on it; a small molecule that binds it is known.
Target class: Writer; Protein methyltransferase; Epigenetic regulator
Chemical probes: CPI-169 (high quality), EPZ011989, EPZ011989 (high quality), UNC1999 (high quality)
Gene: Protein-coding gene on chromosome 17 (42,700,270 to 42,745,060, reverse strand). Ensembl gene ENSG00000108799.
Subcellular location: Nucleus
Subcellular location (Human Protein Atlas): Nucleoplasm
Pathways (Reactome):
Gene expression (Transcription): PRC2 methylates histones and DNA
Gene Ontology:
Molecular function: histone H3K27 methyltransferase activity; histone H3K27 trimethyltransferase activity; molecular condensate scaffold activity; nucleosome binding; protein binding; protein-lysine N-methyltransferase activity; chromatin binding; DNA binding; histone binding; transcription corepressor activity; histone methyltransferase activity
Biological process: anatomical structure morphogenesis; chromatin remodeling; heterochromatin formation; negative regulation of transcription by RNA polymerase II; subtelomeric heterochromatin formation; hippocampus development; positive regulation of transcription by RNA polymerase II
Cellular component: ESC/E(Z) complex; nucleoplasm; nucleus; chromosome, telomeric region; heterochromatin
Genetic constraint (gnomAD): Loss-of-function variants: 32 observed, 97.93 expected, observed/expected ratio (o/e) 0.33, 90% interval 0.25 to 0.44. The upper end of that interval is the gene's LOEUF score, 0.44, which puts it in group 1 of 6, group 1 being the genes least tolerant of losing a copy. Missense variants: 473 observed, 943.51 expected, observed/expected ratio (o/e) 0.5, 90% interval 0.46 to 0.54. Synonymous variants: 270 observed, 324.75 expected, observed/expected ratio (o/e) 0.83, 90% interval 0.75 to 0.92.
Homologues: Orthologues: chimpanzee EZH1 (100% identical), macaque EZH1 (99% identical), dog EZH1 (99% identical), rabbit EZH1 (98% identical), mouse Ezh1 (98% identical), rat Ezh1 (98% identical), pig EZH1 (97% identical), guinea pig EZH1 (95% identical), tropical clawed frog ezh1 (80% identical), Drosophila melanogaster ash1 (14% identical), Drosophila melanogaster Set2 (13% identical), Caenorhabditis elegans met-1 (12% identical), and 16 more. Paralogues in human: EZH2 (65% identical), NSD1 (22% identical), NSD3 (22% identical), NSD2 (22% identical), SETD2 (16% identical), KMT2D (15% identical), ASH1L (14% identical), KMT2C (14% identical), KMT2A (14% identical), EHMT1 (14% identical), EHMT2 (13% identical), KMT2B (13% identical), and 7 more.
Diseases named in the same sentence as EZH1 in open-access papers:
EZH1 is named in the same sentence as 76 diseases in open-access papers, as found by Europe PMC text mining. Sharing a sentence is not in itself a finding about the gene and the disease. The quoted sentences say what the papers report.
breast cancer (9 papers, 2014 to 2025). A primary or metastatic malignant neoplasm involving the breast. "miR-765 is another regulating element of EZH1, and its downregulation is associated with aggravation of breast cancer." (PMID 35087589, 2022). "According to reports, EZH1 participates in the pathogenesis of many cancers, such as breast cancer, lung cancer, prostatic cancer, and hematologic malignancies." (PMID 34976797, 2021). "Currently, the high expression of EZH1 in some tumors, such as in lung cancer, breast cancer, and prostate cancer, suggests that it is closely related to tumorigenesis." (PMID 34976797, 2021). "As inhibition of EZH2/1 and EZH2‐only elicited diametric effects on NKILA expression in the two breast cancer cell lines, we explored the potential contribution of EZH1 to these cell‐specific events." (PMID 31282094, 2019). "In contrast, non‐specific inhibition of EZH2/1 in ER+ breast cancer cells may induce a more robust response over tazemetostat delivery alone, as EZH1 may negatively regulate NKILA under EZH2 inhibition." (PMID 31282094, 2019). "To date, many miR-370-5p-associated regulatory axes have been identified in different cancers, including miR-370-5p/LUC7L3 in breast cancer, miR-370-5p/p21 in lung cancer, and SNHG3/miR-370-5p/EZH1 in colorectal carcinoma." (PMID 35359381, 2022). "While overall levels of EZH1 were higher in HMECs and MDA‐MB‐231 cells, EZH1 levels were more sensitive to EZH2 inhibition in the ER+ breast cancer cell line." (PMID 31282094, 2019).
leukemia (7 papers, 2016 to 2025). A malignant (clonal) hematologic disorder, involving hematopoietic stem cells and characterized by the presence of primitive or atypical myeloid or lymphoid cells in the bone marrow and the blood. "Interestingly, shRNA-mediated inhibition of PRC2 subunit EED, SUZ12, or EZH1/EZH2 causes leukemia cells to stop proliferation and differentiation." (PMID 32436117, 2020). "Double EZH1/2 inhibition increased the efficacy against MLL leukemia compared to single-isoform inhibition." (PMID 34298959, 2021). "The less aggressive leukemia growth observed in EZH1 knockdown compared to control mice was further demonstrated by smaller spleens and less infiltration of leukemia cells into spleens, lungs, and livers." (PMID 31699991, 2019). "The key role of these two enzymes was confirmed, showing that inactivation of EZH1/2 eradicated quiescent leukemia stem cells, inducing cell cycle progression and differentiation." (PMID 31247937, 2019). "UNC1999 is a novel SAM-competitive EZH2/EZH1 inhibitor that has demonstrated efficacy in several cancer models such as leukemia, multiple myeloma and colon cancer." (PMID 27449082, 2016). "Thus, an accurate balance of the AML1-ETO, p300, and EZH1 ensures the achievement of leukemia initiation, promotion and progression in hematopoietic cells." (PMID 31699991, 2019). "Collectively, these findings support EZH1 as an interacting partner of AML1-ETO in leukemia cells." (PMID 31699991, 2019). "Recently, it has been demonstrated that leukemia stem cells express the highest levels of enhancer of zeste homolog 1 (EZH1) and 2 (EZH2), two histone-lysine N-methyltransferases that mediate methylation of histone H3 at lysine 27 (H3K27), to maintain the quiescent state." (PMID 31247937, 2019). "In our study, we chose the small molecule compound UNC1999, a dual inhibitor of EZH1 and EZH2, which showed significant efficacy against leukaemia, bladder cancer and colon cancer." (PMID 41372608, 2025). "For example, UNC1999 and SAH-EZH2 peptide (binds EED, resulting in dissociation of EZH1–EED and EZH2–EED complexes) showed activity against MLL leukemia." (PMID 34298959, 2021). "We first examined the expression of EZH1/2 in 122 patient-derived AML samples, and 13 leukemia cell lines." (PMID 31699991, 2019). "Here the authors report that histone lysine methyltransferase EZH1 interacts with AML1-ETO and methylates AML1-ETO at lysine 43, promoting AML1-ETO transcriptional repression in leukemia." (PMID 31699991, 2019). "In summary, our data demonstrate that combining PI3K inhibitors with EZH1/2 inhibitors may be a promising therapeutic regimen for AML patients, especially for depleting leukemia-initiating cells to reduce the rate of relapse." (PMID 40791365, 2025). "While EZH1 recruitment enhanced the capability of AML1-ETO to interact with co-regulators, methylated K43 appeared to be more essential for the efficacy of AML1-ETO-induced transcriptional repression in leukemia cells." (PMID 31699991, 2019). "We identified EZH1 as a AML1-ETO interacting partner and demonstrated the non-histone PKMT activity of EZH1 in leukemia." (PMID 31699991, 2019). "Due to the difficulty in exploring oncofusion proteins as druggable targets, our findings serve to provide an innovative therapeutic strategy of targeting the non-histone function of EZH1 and lysine methylation for treatment of AML1-ETO leukemia." (PMID 31699991, 2019).
lung carcinoma (5 papers, 2019 to 2022). "Consistent with the stronger effects observed on cell migration upon Ezh1 depletion, lung cancer patients expressing low levels of EZH1 had a significantly poorer prognosis than patients with higher EZH1 expression." (PMID 31015297, 2019). "Consistently, lung cancer patients expressing low levels of EZH1 had a significantly poorer prognosis than patients with higher EZH1 expression." (PMID 31015297, 2019). "Metformin suppressed the protein and mRNA expressions of euchromatic histone lysine methyltransferase 1, 2 (EHMT1, EHMT2), enhancer of zeste 1, 2 polycomb repressive complex 2 subunit (EZH1, EZH2), lysine methyltransferase 2A, 2B (MLL1, MLL2), and WD repeat domain 82 (WDR82) in lung cancer cells." (PMID 33578894, 2021).
lymphoma (5 papers, 2018 to 2024). A malignant (clonal) proliferation of B- lymphocytes or T- lymphocytes which involves the lymph nodes, bone marrow and/or extranodal sites. "A prominent example is provided by Tazemetostat (Epizyme, Inc.), an EZH1/2 inhibitor in stage I/II clinical trials for treatment of refractory malignant mesothelioma, lymphomas and a number of other tumours." (PMID 30005706, 2018). "EZH1 has been demonstrated to play a key role in the development of various cancers, such as multiple myeloma, lymphoma, and thyroid tumors." (PMID 35846880, 2022). "In addition, a recent study reported that EZH1 is globally distributed in the chromatin of aggressive lymphomas, and both EZH1 and EZH2 play critical roles in the chromatin regulation." (PMID 34771469, 2021).
glioma (4 papers, 2013 to 2025). A benign or malignant brain and spinal cord tumor that arises from glial cells (astrocytes, oligodendrocytes, ependymal cells). "Interestingly, combining ClpP agonists with epigenetic therapies, such as HDAC or EZH1/2 inhibitors, has also been shown to enhance antitumor efficacy in high-grade gliomas." (PMID 41008904, 2025). "Xena Functional Genomics Explorer revealed that higher EZH2, but not EZH1, correlated to shorter survival of glioma patients." (PMID 39184078, 2024). "However, in a cohort which includes low grade gliomas, significant survival benefits were observed for patients with low EZH2, PHF19, CBX8 and PHC2 expression, and high CBX7, CBX6, RYBP and EZH1 expression." (PMID 24260522, 2013).
multiple myeloma (4 papers, 2016 to 2022). "Inhibitors targeting both EZH1 and EZH2 (EZH1/2 dual inhibitors) and EED (EED inhibitor) have also been developed, and these inhibitors show better tumor-eradicating effects than EZH2-specific inhibitors in the treatment of AML, multiple myeloma, and EZH2 inhibitor-resistant DLBCL cells." (PMID 33374737, 2020).
diffuse large B-cell lymphoma (3 papers, 2015 to 2023). "Importantly, EZH1 and EZH2 have been identified as candidate oncogenes in diffuse large B cell lymphoma." (PMID 26405815, 2015).
liver fibrosis (3 papers, 2020 to 2023). "Loss of Ezh1 and Ezh2 in hepatocytes leads to liver fibrosis, impaired liver function and increased susceptibility to the hepatotoxic effects of carbon tetrachloride." (PMID 32428001, 2020). "We also found that Ezh1/Ezh2 deficiency up regulates many genes associated with liver fibrosis and HCC in male liver, and that these changes are seen by 7 weeks of age, which precedes the histopathological changes seen in 8-month-old mice." (PMID 32428001, 2020). "For example, the lower incidence rate of liver fibrosis in women compared with men may be attributed to genes associated with liver fibrosis responding differently to the loss of Ezh1/Ezh2 in the male liver." (PMID 35281024, 2022). "Loss of liver Ezh1 and Ezh2 can impact the onset and progression of liver fibrosis, insofar as male E1/E2-KO livers acquire a nodular appearance with portal and periportal inflammation and collagen deposition by 8 months of age, along with substantial impairment of liver function." (PMID 32428001, 2020). "Further, Ezh1/Ezh2 deficiency in male liver, and to a lesser extent in female liver, led to up regulation of many genes linked to liver fibrosis and liver cancer, which may contribute to the observed liver pathologies and the increased sensitivity of these mice to hepatotoxin exposure." (PMID 32428001, 2020). "The mechanisms by which EZH1/EZH2 protect against liver fibrosis were shown to involve the action of these enzymes at euchromatic chromatin bivalently marked with H3K27me3/H3K4me3 at the pro-fibrotic gene promoters." (PMID 37476157, 2023). "In three independent studies using mouse models of liver fibrosis, loss of EZH1 and EZH2 function led to the activation of fibrosis-related genes and the development or worsening of liver fibrosis." (PMID 37476157, 2023). "Genes up-regulated in common in advanced human liver fibrosis and in Ezh1/2-KO mouse liver include biomarkers of liver disease (e.g. Golm1) and genes that play a fundamental role in liver fibrogenesis and HCC (e.g., Spp1/Osteopontin)." (PMID 32428001, 2020). "Finally, we show that many genes associated with liver fibrosis and liver carcinogenesis are differentially responsive to the loss of Ezh1/Ezh2 in male compared to female liver, which may contribute to the observed sex-differences in the incidence and progression of liver cancer." (PMID 32428001, 2020). "Finally, we found that liver fibrosis- and HCC-associated genes are differentially responsive to the loss of Ezh1/Ezh2 in male compared to female liver, which may contribute to the sex differences in disease incidence and progression." (PMID 32428001, 2020). "In contrast to EZH2’s role in promoting HSC activation for liver fibrosis, several studies suggest that EZH1 and/or EZH2 have protective roles in liver fibrosis." (PMID 37476157, 2023). "Significant differences in the regulation of liver fibrosis and HCC-related genes by Ezh1/Ezh2 are seen in male compared to female liver, which may contribute to the sex bias in liver disease progression." (PMID 32428001, 2020). "Thus, Ezh1/Ezh2-catalyzed H3K27-trimethyation regulates sex-dependent genetic programs in liver metabolism and liver fibrosis through its sex-dependent effects on the epigenome, and may thereby determine the sex-bias in liver disease susceptibility." (PMID 32428001, 2020).
prostate carcinoma (3 papers, 2017 to 2023). A carcinoma that arises from epithelial cells of the prostate gland. "In TCGA database, the highest mutation frequency for SPOP was 7.63% (38/498) in prostate cancer, ZNF148 11.25% (9/80) in uveal melanoma 14.3%) and EZH1 11.25% (9/80) in uveal melanoma." (PMID 28580939, 2017). "SPOP mutations have been found in TCGA prostate cancer (10.2%), but with ∼70% has altered either Tryptophan residue at 131 position or Phenylalanine residue at 133 position, while mutations of ZNF148 and EZH1 were commonly observed in melanoma as well with no hot mutation spot." (PMID 28580939, 2017).
T-cell lymphomas (3 papers, 2021 to 2023). "In this study, EZH1/2 mutation status was evaluated in 33 monomorphic epitheliotropic intestinal T-cell lymphomas by next generation sequencing and EZH1/2 and H3K27me3 protein expression levels were detected by immunohistochemistry in 46 T-cell lymphomas." (PMID 34944658, 2021). "In conclusion, EZH1/2 protein expression had opposing effects on the prognosis of T-cell lymphoma patients." (PMID 34944658, 2021). "Overall, T-cell lymphomas show a heterogeneous and so far insufficiently characterized profile of EZH1, EZH2, and H3K27me3 expression as well as a poorly studied correlation of these proteins with each other and with clinicopathological markers." (PMID 34944658, 2021). "Despite the rapid development of new drugs inhibiting EZH2 and/or EZH1, the molecular interplay of these proteins and the impact on disease progression and prognosis of patients with T-cell lymphomas remains insufficiently understood." (PMID 34944658, 2021). "Valemetostat is a dual EZH1/2 inhibitor that has shown activity in both B and T cell NHLs in the Japanese population with an ORR of 53% with a particularly high response rate in T cell NHLs (ORR = 80%)." (PMID 34193230, 2021). "Moreover, compared with normal lymph node tissues, EZH2 and H3K27me3 proteins were found to be overexpressed in T-cell lymphomas, whereas EZH1 was underexpressed, which is consistent with previous reports." (PMID 34944658, 2021). "In this study, we evaluated the EZH1/2 mutation status in a cohort of 33 MEITL by NGS and investigated the immunohistochemical protein expression of EZH1, EZH2, and H3K27me3 in combination with the clinical outcomes in 46 patients with T-cell lymphomas." (PMID 34944658, 2021). "Targeting of both EZH1 and EZH2 enzyme activity may serve as a target for anticancer therapy in T-cell lymphomas." (PMID 34944658, 2021). "Thus, we can conclude that EZH1 and EZH2 have the opposite impact on the OS in the T-cell lymphomas cohorts studied." (PMID 34944658, 2021). "In addition, further mechanistic experiments are required to elucidate the molecular mechanisms of EZH1 and EZH2 in T-cell lymphomas." (PMID 34944658, 2021). "Mutations of EZH1 and/or EZH2 are described as rare or absent in T-cell lymphomas by a number of groups." (PMID 34944658, 2021).
B cell lymphoma (2 papers, 2022 to 2026). "SAM-competitive EZH1 and EZH2 dual inhibitors have been approved by the FDA for treating B-cell lymphoma and other cancers." (PMID 42314051, 2026). "However, at least at the RNA level, we could not detect the altered expression of the major H3K27-HMT EZH1 and EZH2, which other studies have shown in force-stressed HPdLSCs and pathogenically stimulated human B cell lymphoma cells, such as BCBL1." (PMID 35326406, 2022).
colon cancer (2 papers, 2016 to 2025). "Altogether, this study reveals new findings for the role of EZH1-mediated H3K27me1 deposition in maintaining gene silencing while providing rationale for effective epigenetic combination therapies in colon cancer." (PMID 41000734, 2025). "Consequently, colon cancer cells with high levels of EZH1 respond differentially to dual EZH1/2 and EZH2-selective inhibitors when combined with DNMTi." (PMID 41000734, 2025). "To test the contribution of EZH1 to H3K27 methylation state, we selected RKO out of a panel of colon cancer cell lines, as it has high expression of both EZH1 and EZH2 at the protein level." (PMID 41000734, 2025). "To test this hypothesis in cancer cell lines, we compared RKO, which has high expression of EZH1 at the protein level, to SW620, a colon cancer cell line expressing low levels of EZH1." (PMID 41000734, 2025).
glioblastoma (2 papers, 2022 to 2024). The most malignant astrocytic tumor (WHO grade IV). "Glioblastoma-EV-packaged miR-27a-3p could promote M2 macrophage polarization via the EZH1/KDM3A/CTGF axis, and contribute to glioblastoma cell proliferation and motility, thereby increasing GSC tumorigenicity in vivo." (PMID 38379858, 2024).
liver cancer (2 papers, 2020 to 2021). An epithelial or non-epithelial malignant neoplasm that arises from the liver. "Both the lentiviral knockdown and the pharmacological inhibition of EZH1/2 diminished the level of H3K27me3 and suppressed cell growth in liver cancer cells, compared with EZH1 or EZH2 single knockdown." (PMID 34725436, 2021). "Next, we examined EZH1/2 expression and H3K27me3 levels in liver cancer cells treated with sorafenib." (PMID 34725436, 2021).